MT1JP (metallothionein 1J, pseudogene )
Synonyms: MT1; MT1J; MT1NP; MTB
Gene: Long non-coding RNA gene on chromosome 16 (56,635,712 to 56,637,086, forward strand). Ensembl gene ENSG00000290662.
Diseases named in the same sentence as MT1JP in open-access papers:
MT1JP is named in the same sentence as 18 diseases in open-access papers, as found by Europe PMC text mining. Sharing a sentence is not in itself a finding about the gene and the disease. The quoted sentences say what the papers report.
gastric cancer (27 papers, 2018 to 2025). A primary or metastatic malignant neoplasm involving the stomach. "We aim to draw an objective conclusion of the association between MT1JP expression levels with OS for gastric cancer patients." (PMID 29794726, 2018). "For example, lncRNA MT1JP is associated with gastric cancer (GC) survival." (PMID 39210921, 2024). "Randomized controlled trials (RCTs), prospective cohort studies, and case–control studies will be used for the qualitative and quantitative synthesis of the meta-analysis to explore the association between MT1JP expression levels with OS for gastric cancer patients." (PMID 29794726, 2018). "Rescue experiments showed that downregulation of FBXW7 reversed MT1JP-induced inhibition of gastric cancer proliferation, invasion, and migration." (PMID 40534867, 2025). "Rescue experiments exhibited that downregulation of FBXW7 reversed MT1JP-induced inhibition of proliferation, invasion and migration in gastric cancer." (PMID 35928868, 2022). "In gastric cancer, lncRNA MT1JP binds miR-92a-3p to regulate FBXW7 expression, which in turn affects gastric cancer progression." (PMID 35646642, 2022). "The expression level of MT1JP was shown to be significantly lower in gastric cancer, hepatocellular carcinoma and lung cancer tissues (especially for lymph node metastasis and advanced-stage cancer) than that in adjacent normal tissues." (PMID 35270630, 2022). "In vitro experiment data showed that lncRNA MT1JP upregulation suppressed proliferation, invasion and migration and enhanced apoptosis of gastric cancer cells." (PMID 35928868, 2022). "LncRNA metallothionein 1 J, pseudogene (MT1JP) has been reported to be downregulated in cancers developed from liver, lung, colon and gastric cancer, suggesting its tumor suppressive role." (PMID 35703312, 2022). "In gastric cancer, lncRNA MT1JP as ceRNA sponges miR-92a-3p to regulate the expression of FBXW7 and then influence the progression of gastric cancer." (PMID 33968763, 2021). "The tumor-suppressing role of MT1JP has been reported in multiple cancer cells, including breast cancer, glioblastoma, bladder cancer and gastric cancer." (PMID 33557774, 2021). "On the other hand, LncRNA MT1JP expression is decreased in gastric cancer, and it inhibits the process of gastric cancer through competitively binding to miR-92a-3p and regulating the expression of FBXW7." (PMID 34789303, 2021). "In gastric cancer, lncRNA MT1JP regulated the expression of FBXW7 through competitively binding with miR-92a-3p, and played a role in inhibiting cell proliferation, migration, invasion and promoting cell apoptosis." (PMID 32661236, 2020). "For example, the lncRNA MT1JP regulates FBXW7 as a ceRNA by interacting with miR-92a-3p in gastric cancer." (PMID 33323548, 2020). "For instance, MT1JP functioned as a ceRNA to regulate FBXW7 in gastric cancer via sequestering miR-92a-3p." (PMID 32565736, 2020). "Both LncRNA BDNF-AS and MT1JP have been reported decreased in quite a few cancers including gastric cancer, bladder cancer and lung cancer, suggesting their potential role as a rather broad and sensitive tumor suppresser." (PMID 32514246, 2020). "In terms of BC, one recent study presented the first evidence that MT1JP overexpression markedly inhibits invasion and enhances cisplatin sensitivity of BC cells, which is coincident with gastric cancer results." (PMID 31744046, 2019). "In line with the our results, a previous study applied an mRNA/lncRNA microarray in 76 pairs of tumor and normal tissue sample from live, colon, lung and gastric cancer, and revealed that lncRNA MT1JP had remarkably lower expression in all tumor samples." (PMID 29720189, 2018). "MT1JP regulates gastric cancer progression by binding to miR-92a-3p competitively with FBXW7." (PMID 35430805, 2022).
gastric cancer (continued). "MT1JP is down-regulated in gastric cancer tissues and may serve as a disease progression biomarker and a potential therapeutic strategy." (PMID 35346215, 2022). "LncRNA MT1JP was downregulated in gastric cancer tissues compared with adjacent normal tissues." (PMID 35928868, 2022). "lncRNA MT1JP functioned as a ceRNA to regulate miR-92a-3p/FBXW7 in gastric cancer." (PMID 35936736, 2022). "Gastric cancer patients had a better prognosis, who often have higher expression of MT1JP." (PMID 35928868, 2022). "For example, miR-92a-3p is sponged by MT1JP to regulate the progression of gastric cancer." (PMID 32351327, 2020). "Decreased MT1JP expression is significantly associated with more lymphatic metastasis and advanced Tumor Node Metastasis (TNM) stage for gastric cancer patients, and in-vitro and in-vivo studies have shown the suppressive role of MT1JP on the migration and invasion of gastric cancer." (PMID 31744046, 2019). "Notably, low expression of MT1JP was related with poor prognosis in patients with gastric cancer." (PMID 35928868, 2022). "Mechanistic analysis showed that lncRNA MT1JP recruited miR-92a-3p and upregulated FBXW7 in gastric cancer." (PMID 40534867, 2025). "Although expression of miR-92a-3p is elevated in gastric cancers, the ceRNA activity of lncRNA MT1JP can efficiently prevent miR-92a-3p repression of FBXW7 mRNA expression and induce apoptosis of gastric cancer cells." (PMID 35346215, 2022). "Mechanistical analysis demonstrated that lncRNA MT1JP sponged miR-92a-3p and upregulated FBXW7 in gastric cancer." (PMID 35928868, 2022). "MT1JP regulated miR-214-3p/RUNX3 signaling pathway and subsequently inhibited proliferation and migration of gastric cancer." (PMID 35928868, 2022). "The lncRNA MT1JP (metallothionein 1J, pseudogene) increases expression levels of FBXW7 and inhibits proliferation and invasion of gastric cancer cells." (PMID 31248165, 2019). "Subsequently, MT1JP was found as a ceRNA to bind to miR-214-3p to facilitate expression of runt related transcription factor 3 (RUNX3), and suppressed cell proliferation, invasion and migration in gastric cancer cells." (PMID 33557774, 2021). "MT1JP, which severs as a ceRNA regulating FBXW7 expression, could influence the progression of gastric cancer." (PMID 34196116, 2021). "Moreover, MT1JP regulates FBXW7 and inhibits gastric cancer via binding to miR-92a-3p." (PMID 31248165, 2019). "Although several researches have investigated the association between development and metastasis of gastric cancer (GC) and the expression level of MT1JP, there are no consensuses about whether its expression is associated with overall survival (OS) and clinical feature for GC patients." (PMID 29794726, 2018).
breast carcinoma (6 papers, 2021 to 2022). "MT1JP was also reported to inhibit biological activities of breast cancer cells in vitro and in vivo by regulating the miRNA-214/RUNX3 axis." (PMID 35703312, 2022). "MT1JP overexpression specifically sensitized breast cancer cells to cisplatin treatment by targeting miR-24-3p." (PMID 36613528, 2022). "MT1JP was downregulated in breast cancer samples and its overexpression inhibited cell proliferation by downregulating miR-24-3p in breast cancer cells." (PMID 36613528, 2022). "In breast cancer cells, MT1JP repressed oncogenesis and reversed cisplatin resistance through sponging miR-24-3p and inhibiting the Wnt/β-catenin." (PMID 35928868, 2022). "In this study, overexpression of MT1JP in breast cancer cells significantly inhibited their proliferation and enhanced their cisplatin sensitivity, which seems to be discordant with our results." (PMID 33974236, 2021). "Another recent study also showed that MT1JP was downregulated in breast cancer." (PMID 35703312, 2022). "It has been reported that Lnc-408 upregulates LIMK1 signaling pathway via sponging miR-654-5p, thereby accelerating breast cancer metastasis and invasion, and Lnc-MT1JP has been proved to enhance the resistance of hepatocellular carcinoma cells to Lenvatinib via sponging miR-24-3p." (PMID 35012431, 2022). "MT1JP acts as a tumor suppressor by regulating miR-92-3p in breast cancer cells." (PMID 35703312, 2022). "Consistently, MT1JP exhibited tumor suppressive functions via sponging miR-92-3p and targeting miR-214/RUNX3 axis in breast cancer cells." (PMID 35928868, 2022).
lymph node metastasis (4 papers, 2018 to 2023). "Furthermore, our study found that expression of lncRNA MT1JP was prominently associated with lymph node metastasis and advance stage, suggesting a clinic pathological role of lncRNA MT1JP in GC." (PMID 29720189, 2018). "The MT1JP low expression is more common in patients with advanced stage or/and existence of lymph node metastasis." (PMID 33557774, 2021). "LncRNA MT1JP was significantly lower in GC tissues than adjacent normal tissues, and higher MT1JP was remarkably related to lymph node metastasis and advance stage." (PMID 29720189, 2018). "The expression level of MT1JP was significantly related with TNM stage and lymph node metastasis." (PMID 33557774, 2021).
bladder cancer (3 papers, 2020 to 2021). "MT1JP has previously been reported to act as a tumor suppressor in breast and bladder cancer and it has been reported that MT1JP may inhibit the proliferation, invasion and migration of tumor cells." (PMID 33974236, 2021).
lung carcinoma (3 papers, 2020 to 2022). "LncRNAs such as lnc ADAMTS9-AS2, MT1JP, and GAS5 act as tumor suppressors in lung cancer through lncRNA/miRNA ceRNA networks, which regulate the expressions of well-known tumor suppressors such as PTEN and TIMP2." (PMID 33412752, 2020). "In addition, lncRNAs such as MT1JP, MAGI2-AS3, PLAC2, TINCR, LINC00641, FENDRR (FOXF1 adjacent non-coding developmental regulatory RNA), TRHDE-AS1, and lncRNA-p21 act as tumor suppressors in lung cancer by sponging miRNAs." (PMID 33412752, 2020).
cholangiocarcinoma (2 papers, 2021 to 2024). A carcinoma that arises from the intrahepatic biliary tree (intrahepatic cholangiocarcinoma) or from the junction, or adjacent to the junction, of the right and left hepatic ducts (hilar cholangiocarcinoma). "LncRNA MT1JP is downregulated in cholangiocarcinoma tissues, and its expression is associated with TNM staging and lymph node metastasis." (PMID 38637832, 2024). "Gain- and loss-of-function experiments demonstrated that MT1JP inhibited cell proliferation, cell cycle transition, migration and invasion, and promoted apoptosis in cholangiocarcinoma cells." (PMID 33557774, 2021). "The present study aimed to verify the hypothesis and investigated the effect of MT1JP in cholangiocarcinoma cells via gain- and loss-of-function experiments." (PMID 33557774, 2021). "The results in this section demonstrated that MT1JP was downregulated and miR-18a-5p was upregulated in cholangiocarcinoma specimens." (PMID 33557774, 2021). "The TCGA database shows that MT1JP is downregulated in cholangiocarcinoma specimens, and its expression is positive correlated with that of fructose-1,6-bisphosphatase 1 (FBP1)." (PMID 33557774, 2021). "MT1JP alleviated proliferation, migration and invasion, and induced apoptosis in cholangiocarcinoma cells by regulating miR-18a-5p/FBP1 axis." (PMID 33557774, 2021). "In order to investigate the roles of MT1JP in cholangiocarcinoma cells, MT1JP overexpresion plasmid was transfected into HCCC-9810 cells, and its siRNA was transfected into HUCCT1 cells." (PMID 33557774, 2021). "In this study, we found that MT1JP was downregulated in clinical cholangiocarcinoma specimens, and its expression was correlated with TNM stage and lymph node metastasis." (PMID 33557774, 2021). "Subsequently, twelve paired of intrahepatic cholangiocarcinoma specimens were used for detection of MT1JP and miR-18a-5p expression levels by real-time PCR." (PMID 33557774, 2021). "In addition, miR-18a-5p was increased in cholangiocarcinoma tissues, which was negatively correlated with that of MT1JP." (PMID 33557774, 2021). "MT1JP was decreased and miR-18a-5p was increased in intrahepatic cholangiocarcinoma cells." (PMID 33557774, 2021). "CCK-8 assay showed that MT1JP inhibited cell viability in cholangiocarcinoma cells." (PMID 33557774, 2021). "In addition, GEPIA website showed that the expression level of MT1JP was positively correlated with that of FBP1 in cholangiocarcinoma tissues." (PMID 33557774, 2021). "According to TCGA database, MT1JP and FBP1 were downregulated and miR-18a-5p was upregulated in clinical cholangiocarcinoma tissues." (PMID 33557774, 2021). "The tumor-suppressing role of MT1JP has been verified in multiple cancer types, but its effect on cholangiocarcinoma has not been evaluated." (PMID 33557774, 2021). "Because MT1JP has previously been reported to act as a miRNA sponge, we hypothesized that MT1JP functioned by sponging miR-18a-5p and regulating FBP1 expression in cholangiocarcinoma." (PMID 33557774, 2021).
intrahepatic cholangiocarcinoma (2 papers, 2021 to 2024). A carcinoma that arises from the intrahepatic bile duct epithelium in any site of the intrahepatic biliary tree. "The results in this section suggested that MT1JP retarded tumorigenesis of intrahepatic cholangiocarcinoma cells in nude mice." (PMID 33557774, 2021). "MiR-18a-5p was increased in intrahepatic cholangiocarcinoma samples, and its expression was negatively correlated with that of MT1JP." (PMID 33557774, 2021). "The results in this sections suggested that MT1JP inhibited proliferation and promoted apoptosis in intrahepatic cholangiocarcinoma cells." (PMID 33557774, 2021). "In this study, we demonstrated that lncRNA MT1JP was downregulated in intrahepatic cholangiocarcinoma tissues." (PMID 33557774, 2021). "As MT1JP was decreased in intrahepatic cholangiocarcinoma tissues, its expression was examined in several intrahepatic cholangiocarcinoma cell lines and normal primary intrahepatic cholangetic epithelial cells." (PMID 33557774, 2021). "MT1JP was downregulated in intrahepatic cholangiocarcinoma specimens, and its expression was related with TNM stage and lymph node metastasis." (PMID 33557774, 2021). "The expression of MT1JP in intrahepatic cholangiocarcinoma specimens and paired para-carcinoma tissues were detected by real-time PCR." (PMID 33557774, 2021). "Overexpression of MT1JP inhibited proliferation, cell cycle transition, migration and invasion, and induced apoptosis in intrahepatic cholangiocarcinoma cells." (PMID 33557774, 2021). "In this study, we analyzed the correlation between MT1JP expression and clinical characteristics of thirty intrahepatic cholangiocarcinoma patients, and found that the expression level of MT1JP was related with TNM stage and lymph node metastasis." (PMID 33557774, 2021). "The results in this section suggested that MT1JP suppressed migration and invasion in intrahepatic cholangiocarcinoma cells." (PMID 33557774, 2021). "MT1JP inhibited proliferation, migration, invasion and tumorigenesis and enhanced apoptosis in intrahepatic cholangiocarcinoma cells as a miRNA sponge to bind to miR-18a-5p to facilitate the expression of FBP1." (PMID 33557774, 2021). "The overexpression plasmid and siRNA of MT1JP were transfected into intrahepatic cholangiocarcinoma cells to change the expression levels of MT1JP." (PMID 33557774, 2021). "Moreover, the expression of MT1JP was significantly decreased in intrahepatic cholangiocarcinoma samples." (PMID 33557774, 2021).
glioma (1 paper, 2021). A benign or malignant brain and spinal cord tumor that arises from glial cells (astrocytes, oligodendrocytes, ependymal cells). "In glioma and glioblastoma, MT1JP is downregulated in patient tissues and cell lines." (PMID 34947885, 2021).
liver cancer (1 paper, 2023). An epithelial or non-epithelial malignant neoplasm that arises from the liver. "However, the selection of MT1JP as a biomarker in liver cancer is complicated by its apparent dual roles: in addition to being associated with lenvatinib resistance owing to its antiapoptotic ability, some studies have noted that MT1JP is actually a tumor suppressor." (PMID 36980210, 2023).
osteosarcoma (1 paper, 2025). A usually aggressive malignant bone-forming mesenchymal neoplasm, predominantly affecting adolescents and young adults. "Based on RT-qPCR results, plasma MT1JP levels were significantly lower in osteosarcoma patients than in controls." (PMID 39797974, 2025).
retinoblastoma (1 paper, 2020). A malignant tumor that originates in the nuclear layer of the retina. "LncRNAs PVT1, AFAP10AS1, HOTAIR, BANCR, H19, DANCR and LINC00202 were up-regulated in retinoblastoma tissues while MT1JP and BDNF-AS were down-regulated." (PMID 32514246, 2020). "Based on all eligible evidence, we found two lncRNAs:BDNF-AS and MT1JP as potential prognostic biomarker for retinoblastoma." (PMID 32514246, 2020). "LncRNA MT1JP and BDNF-AS were slightly decreased in retinoblastoma tissues, which was consistent with our analysis." (PMID 32514246, 2020).